MYD88 (MYD88 innate immune signal transduction adaptor)
Diseases named in the same sentence as MYD88 in open-access papers (continued):
Sharing a sentence is not in itself a finding about the gene and the disease.
infection (continued). "Thus, the coordinated integration of signals triggered by the activation of CLR/CARD9, IL-1R1/MyD88, and TLR/MyD88 pathways are critical for the attraction of phagocytes to the site of infection." (PMID 36752587, 2023). "Additionally, MYD88 signaling was also significant for DCs to produce proinflammatory cytokines, mediate neutrophil infiltration, and protect against infection." (PMID 37175545, 2023). "The infection with Salmonella upregulated MyD88 mRNA expression." (PMID 38003758, 2023). "To dissect the mechanisms of MyD88‐dependent killing of C. burnetii, we explored the expression of several genes with known or assumed anti‐microbial function in the spleen of mice after intraperitoneal infection with NMII." (PMID 36479617, 2023). "In vivo infection experiments have demonstrated that CD mucosa-associated E. coli killing by macrophages could be inhibited by microbial mannan in a TLR4 and MyD88-dependent manner." (PMID 37311220, 2023). "Rather, the downregulation of TLR4 and TLR6 in response to T15 and S10 infection, respectively, as well as the downregulation of expression of the adapter protein MYD88 during 8067 and T15 infection, was seen (albeit at low-fold changes, especially during T15 infection)." (PMID 38276150, 2023). "Pax5+/−;Myd88+/− mice were exposed to natural infections, and B-ALL development was monitored." (PMID 37620322, 2023). "Interestingly, our DSP analysis of hamster lung tissues showed that the MyD88-independent/TRIF-dependent TLR4 pathway was the top enriched TLR4 cascade after two days of infection." (PMID 37369668, 2023). "Notably, the virulence of the LVS ∆tolC mutant was fully restored in the MYD88−/− mice, with all mice succumbing to infection with kinetics similar to mice infected with the WT bacteria." (PMID 37404047, 2023). "First, we decreased the expression of Myd88 by generating Pax5+/−;Myd88+/− mice by interbreeding, and examined whether Pax5+/−;Myd88+/− animals were more prone to infection-induced B-ALL than Pax5+/− mice." (PMID 37620322, 2023). "We next compared infection of WT and MYD88−/− mice with the WT or ∆tolC LVS." (PMID 37404047, 2023). "MyD88 signalling is crucial for mice to combat L. pneumophila infection, as it triggers the early secretion of inflammatory cytokines, neutrophil recruitment, and the host immune response to the infection." (PMID 37155695, 2023). "The upregulation of the expression level of IL-1β, TNF-α, and Myd88 indicates that GF-7 supplementation might induce an immune response in M. salmoides, and enhance the body’s resistance to foreign infection." (PMID 37333660, 2023). "However, in vitro infection of macrophages deficient in TLR2, TLR4, and MyD88 by L. amazonensis is higher than wild-type counterparts." (PMID 37000792, 2023). "The expression profiling of TLR signaling pathway genes after pathogen stimulation showed that the infection of pathogens induced the activation of (TLR1-2) - MyD88 - FADD - Caspase 8 involved signaling pathway, and inhibits the spread of bacteria in the body through cell apoptosis." (PMID 37056759, 2023). "In addition, defective PTX3 production after intranasal infection with S. pneumoniae was observed in Il1r−/− mice, as well as in Myd88−/− animals." (PMID 37222419, 2023). "In lethal Plasmodium yoelii YM infection, it’s plasmacytoid cells (pDCs) that sense the infection through TLR7 and produce a large amount of IFN-α and IFN-β via Myd88-dependent IFN regulatory factor (IRF) 7 transcription factor-mediated type I IFN signaling in the first 24 hours post infection." (PMID 37180169, 2023). "In addition, layers challenged with E. tenella have been shown to exhibit a 2 fold increase in the up-regulation of TLR15, NF-κB, and MyD88 gene expression in their ceca between 4 and 24 h post infection." (PMID 36230268, 2022).
infection (continued). "Previously, our group identified the crucial role of T cell-intrinsic IL-18R/MyD88 signaling for the reinforcement and maintenance of the Th1 program in vivo, in response to mouse infection with Trypanosoma cruzi, in which Th1 cells have a key protective function." (PMID 35670567, 2022). "Hence, the MyD88 KO mice inoculated with 107 CFU developed a sufficient level of colonization and shed B. pertussis efficiently enough to consistently transmit the infection onto co-housed recipient MyD88 KO cage mates." (PMID 35395059, 2022). "In addition, Tm-MyD88 silencing attenuates resistance to S. aureus in T. molitor, suggesting that Tm-MyD88 is required for survival against infection due to the Gram-positive S. aureus." (PMID 36296259, 2022). "Indeed, the C57BL/6J mice resisted infection even when co-housed with the MyD88 KO mice inoculated by 107 CFU, which shed rather high numbers of B. pertussis bacteria." (PMID 35395059, 2022). "The results show that the levels of phospho-NF-κB p65, p-IκB, and MyD88 proteins increased with infection time from 3 to 12 h post-infection and decreased after 48 h post-infection, indicating that the MyD88/NF-κB signaling pathway is activated early in ASFV infection." (PMID 35215890, 2022). "MyD88−/− mice showed lower inflammation with fewer neutrophils after infection with 5-ASKH." (PMID 36190414, 2022). "Moreover, the percentages of CD11b+Ly6ChiLy6G– cells were much lower in Tmem173gt, Mb21d1–/–, Myd88–/–, and Mavs–/–Il6–/– mice than in WT and Mavs–/– mice at day five after N67C infection." (PMID 35635376, 2022). "Although single-PEDV infection showed up-regulation on cell-membrane- (TLR4) and endosomal-associated (TLR3 and TLR8) TLRs by 5 DPI, it seems that these TLRs did exert a sufficient modulatory effect on MyD88 and TRIF." (PMID 36376395, 2022). "It has been indicated that infections of macrophages from MYD88−/− mice with SbRLD significantly enhance the intracellular Leishmania parasite number coupled with the increased IL-10/IL-12 ratio in the culture supernatant in comparison with infections of wild type (WT) macrophages." (PMID 34218829, 2021). "We speculated that a high infection dose might result in a saturated immune response controlled by different pathways (e.g., Toll-like receptor (TLR) 2/MyD88 pathway) and this would hinder the effect of CXCR3 loss." (PMID 34835465, 2021). "Further elucidation of MyD88-independent pathways of mucosal immunity may shed light on how humans sense infection and mount immune responses to Toxoplasma and other microbial pathogens in the absence of MyD88." (PMID 34597344, 2021). "The lower number of leukocytes observed at the site of infection in myd88-/- larvae could either be due to a lower number of leukocytes recruited to the infected area or to a higher rate of cell death of these cells." (PMID 33559740, 2021). "Thus, while MyD88 signaling in maternal B cells protects the mother from infection, it ultimately kills the fetus." (PMID 34685673, 2021). "GRA15 was more abundant in RH versus PTG but interestingly only during infection of MyD88−/− BMDM." (PMID 33622246, 2021). "Thus, determining MyD88-independent responses to infection with Toxoplasma and other microbial pathogens is an important avenue of investigation in both humans and mice." (PMID 33622246, 2021). "This realization has sparked new interest in identification of MyD88/TLR independent mechanisms of Toxoplasma recognition that may be relevant to human infection." (PMID 34597344, 2021). "MyD88 expression was down-accumulated at the four time points after infection, suggesting that IFN expression may also be affected." (PMID 34113672, 2021). "However, it was observed that levels of Clostridiales dropped significantly in Myd88−/− post infection as compared to uninfected samples especially at 3 months." (PMID 33477306, 2021).
infection (continued). "Thus, MyD88 interaction with IRF3/IRF7 is linked to weak immune signaling and curtail IFN-β induction which is critical at the early stage in clearing the infection." (PMID 33834387, 2021). "However, mice deficient in MyD88 have NK cells with defective IFN-γ production and are susceptible to infections." (PMID 34093543, 2021). "However, overexpressing Neu1 and silencing siglec-E together followed by infection was able to effectively upregulate both MyD88- and TRIF-dependent pathways of TLR4 activation." (PMID 33763070, 2021). "In our present study, we confirmed that TLR signaling-related genes, including Tlr4, Nfkb, Myd88, Cd14, Il6 and Tnf, are gradually increased in the AP mouse model following induction of the infection and become highly expressed when lesion formation accompanied by bone destruction is established." (PMID 33510341, 2021). "In addition, the myd88 mutant larvae showed more compacted aggregations of Mm at the site of infection than the wild types." (PMID 33559740, 2021). "MyD88 is a key downstream molecule in the inflammatory signaling pathway that also plays an important role in the regulation of cellular mediated immunity during infection." (PMID 32973780, 2020). "Therefore, to identify the critical receptors upstream of MyD88, we investigated craniotomy infection in TLR2 and TLR9 knockout (KO) mice." (PMID 32290861, 2020). "When challenged with E. faecalis, Med31 RNAi flies displayed a sensitivity to this infection that was intermediate between those of MyD88 and wild-type control flies in seven out of nine experiments, whereas they behaved almost like wild-type flies in the two other experiments." (PMID 33746938, 2020). "To determine if MyD88 is the main adaptor protein in TLR2 signaling and to examine the effect of nicotine on MyD88 signaling and subsequent proinflammatory cytokine IL-8 in macrophage during infection, we measured expression of MyD88 and IL-8 following nicotine treatment of MAP-infected macrophages." (PMID 33212859, 2020). "Likewise, MAP viability in macrophages treated with anti-MyD88 decreased to 55% but after 48 h infection." (PMID 33212859, 2020). "In contrast, another study found that MyD88−/− mice were not more susceptible to paracoccidioidomycosis, as measured by quantitative culture, in an intravenous infection model." (PMID 32545735, 2020). "Moreover, the lung cytokine profile and the production of ROS were less affected by infection in MyD88–/– mice than in TLR4–/– mice, although these responses were weaker than in infected WT mice." (PMID 33042124, 2020). "Surprisingly, dual treatment of MAP-infected macrophages with MyD88 antagonist and nicotine absolutely impaired immune response and decreased MAP viability, which clearly validate the inflammatory role of nicotine in macrophages through TLR2/MyD88 pathway during infection." (PMID 33212859, 2020). "To determine whether the other MyD88-dependent signal responsible for iNOS induction originated from IL-1R, we treated mice with an IL-1R blocking mAb at the time of infection." (PMID 31999809, 2020). "Thus, while TLR/MyD88 signaling plays a major role in rodent resistance to Toxoplasma and other infections, this signaling axis appears less crucial for defense in humans." (PMID 32413093, 2020). "Therefore, MyD88 is required in Tregs for their basal proliferation and enhancing Th17 functions at early time-points of infection." (PMID 33240286, 2020). "Our data suggest that SIGIRR localizes in the membrane and the cytosol and associates with MyD88 in uninfected cells, but some SIGIRR may also associate with the C. trachomatis inclusion during infection, according to our immunoprecipitation results." (PMID 32210474, 2020). "However, there are some notable changes in titer at 72 h and in some genes including Myd88, Caspar, and rel2 at 168 h after infection." (PMID 32630843, 2020). "The role of MyD88 in innate immunity to infection is controversial." (PMID 32545735, 2020).
infection (continued). "However, given that the pulmonary route of infection is more physiologic, it is more likely that MyD88 plays a role in resistance." (PMID 32545735, 2020). "Compared with MAP infection alone, nicotine upregulated MyD88 and IL-8 expression, the latter showed more noticeable change of 2.5-fold (MAP + nicotine: 22.3 ± 2.09 vs. MAP alone: 13.39 ± 1.80; p < 0.05, for MyD88), (MAP + nicotine: 6.40 ± 0.52 vs. MAP alone: 3.52 ± 0.62; p < 0.05, for IL-8)." (PMID 33212859, 2020). "In A. aegypti, silencing of MyD88 led to a significant increase in dengue virus titers, demonstrating the importance of this innate immune pathway in the defense against different dengue virus serotypes at the early stages of infection." (PMID 33488623, 2020). "However, restoration of MyD88 signaling in DCs only is sufficient to regain control over the infection." (PMID 33584721, 2020). "Our results reveal a previously unknown role of the IL-1β/MyD88/mTOR axis in modulating mucosal Tregs during an infection." (PMID 33240286, 2020). "We speculated that there is a link between the high expression of TLRs in macrophages with the MyD88-dependent pathway and the proinflammatory response during infection in Crohn’s disease." (PMID 33212859, 2020). "In the livers of Myd88+/− mice granuloma-like structures consisting of infiltrated leukocytes were easily detectable on day 5 and to a lesser extent on day 20 after infection, reflecting the massive reduction in bacterial load at the later time point in Myd88+/− mice." (PMID 30800124, 2019). "On the other hand, the absence of the two MyD88 alleles (MyD88-/-inf) showed no infection deleterious impact in the placental vasculature, identical to the non-infected controls (dashed line)." (PMID 30761111, 2019). "Notably, H. felis infection significantly increased Tnfsf14 expression in the stomach of Myd88−/− mice, while only a slight increase was detected in WT animals after 25 weeks of infection." (PMID 31065023, 2019). "Together, these results indicate that, unlike the case in early infection, MyD88-independent systemic inflammation is associated with lung pathology during the disease phase." (PMID 30642901, 2019). "Thus, MyD88 signaling during IOE infection plays a protective role by attenuating bacterial survival and replication via inhibition of autophagy induction." (PMID 31134081, 2019). "After infection via the natural route by intratracheal injection, a higher bacterial load in the lung and increased dissemination of NMII to other organs was observed in MyD88-deficient mice." (PMID 30800124, 2019). "Wild type and Myd88−/− mice showed large lymphoid structures in the gastric mucosa after infection." (PMID 31065023, 2019). "As with Trif−/− mice, neutrophils showed a significant increase in percentage in MyD88−/−/Trif−/− over wild‐type mice, which could reflect the infection or inflammatory status of these mice." (PMID 31210415, 2019). "The induction of iNOS in macrophages in vitro, and the expression of Arginase-1 and of IL-10 in vivo, was not altered in MyD88-deficient cells/mice after infection with NMII." (PMID 30800124, 2019). "Its expression was reduced in a Myd88−/− mice after infection with NMII." (PMID 30800124, 2019). "In this study, we focused primarily on MyD88 and IL-1R signaling cascades given their established roles in innate immune responses against S. aureus in other models of infection, in concert with the known effects of these signaling pathways on bone cell function." (PMID 30978245, 2019). "To assess whether non-canonical NF-κB signaling could be related to the more severe pathology observed in Myd88−/− mice upon infection with H. felis, we first evaluated nuclear translocation of RelB into the nucleus of gastric epithelial cells." (PMID 31065023, 2019).
infection (continued). "Despite the increased and prolonged presence of NMII in the organ tissues, Myd88−/− mice did not develop signs of clinical disease and in fact were protected from the transient weight loss induced early after infection in Myd88+/− mice." (PMID 30800124, 2019). "However, at 24 h post-infection the transcript levels of MyD88 were higher in larvae challenged with symbiotic (p = 0.0087) or axenic (p = 0.003) nematodes compared to controls." (PMID 29419764, 2018). "Taken together, our data suggest that the absence of MyD88 predisposes animals to hypergammaglobulinemia, production of autoantibodies, and deposition of immune complexes in kidney glomeruli following infection with S. typhimurium." (PMID 29973931, 2018). "At the same time, indicators of inflammatory response such as production of IFN-γ, TNF-α, IL-1β, and IL-6 mediated by TLR/MyD88/NFκB were also activated after N67 infection, which may explain the pathology and host death later in infection." (PMID 30327482, 2018). "Hence, in addition to showing a humoral immune response that is constitutively skewed to Th2-induced IgG isotypes, MyD88−/− mice challenged with attenuated Salmonella display hypergammaglobulinemia due to unresolved infection." (PMID 29973931, 2018). "Furthermore, MyD88 assists in the recognition of L. donovani and maturation of dendritic cells during infection." (PMID 30555476, 2018). "These mice lack MyD88, which is part of the signaling pathway of Toll-like receptors that activates inflammatory cytokine production, and as a result the recruitment of neutrophils and macrophages to the site of infection is impaired." (PMID 27821583, 2017). "Indeed, in mice deficient for MyD88, the adaptor of almost all TLRs except TLR3, the inflammation upon infection with L. interrogans was equivalent to the inflammation found in double TLR2/TLR4ko mice." (PMID 28270811, 2017). "Bone marrow transfer approaches indicated that MyD88 signaling in both the hematopoietic and non-hematopoietic compartments contributes to the infection-associated response." (PMID 28520792, 2017). "MyD88-/- mice displayed a greater bioluminescence signal than WT mice starting at 3 days post infection, and this signal remained elevated until mice were euthanized at 12 days post infection." (PMID 28704551, 2017). "In our high-throughput dataset, while not statistically significant, this microRNA shows an up-regulation in the wild type upon infection (1.26 log2 FC) and a down-regulation in MyD88-/- cells (-2.06 log2 FC), mirroring the expression pattern we show for miR-125a-3p." (PMID 28445535, 2017). "All known mammalian TLR except TLR3 use MyD88-dependent pathways, whereas TLR3 exclusively activates TRIF-dependent pathways, and TLR4 is unique in this regard as it can use all four adapter proteins (TRAM, TRIF, TIRAP, MyD88) to signal infection and injury via both pathways." (PMID 28836991, 2017). "We then examined whether the accumulation of LC3I and LC3II in WT and MyD88-/- BMM was an early or late event during IOE infection." (PMID 29049365, 2017). "We finally tested whether restricting functional expression of MyD88 to IEC has a direct impact on the epithelial barrier integrity during infection." (PMID 28520792, 2017). "Indeed, after infection of BMDMs with L. monocytogenes, DDR activation depends on TLR signaling, as BMDMs deficient in MyD88, a critical TLR adaptor protein, exhibit diminished γ-H2AX formation." (PMID 28362262, 2017). "Although the contribution of Ehrlichia-derived PAMPs to inflammasome activation needs to be investigated, these data suggest that mitochondrial DAMPs are potential ligands for TLR9/MyD88-mediated inflammasome activation during lethal infection with LPS-negative Ehrlichia." (PMID 29049365, 2017). "MyD88 KO were used as a control group and showed the highest CFU numbers in the spleen compared to other strains tested here, indicating their susceptibility to infection." (PMID 28167945, 2017).